RNASE2 (ribonuclease A family member 2)
Diseases named in the same sentence as RNASE2 in open-access papers (continued):
Sharing a sentence is not in itself a finding about the gene and the disease.
infection (7 papers, 2011 to 2022). The state of being infected such as from the introduction of a foreign agent such as serum, vaccine, antigenic substance or organism. "The two prominent RNases, EDN (RNase 2) and ECP (RNase 3), are found in saliva, with increased expression during illness and infection." (PMID 35626342, 2022). "The eosinophil ribonucleases, EDN (eosinophil derived neurotoxin, RNase2) and ECP (eosinophil cationic protein, RNase3), are two secretory ribonucleases stored in the secondary granules of eosinophils and released at the focus of infection." (PMID 27089320, 2016).
bacterial infections (4 papers, 2005 to 2025). "Discrepancy of expression induction is also found for RNase2 secretion by eosinophils upon distinct bacterial infections." (PMID 35347428, 2022). "Our results are not only useful for the research of Rnase2 and Rnase3 evolution, but also help further elucidation of the regulation mechanisms in the innate immune response of M. amblycephala to bacterial infection." (PMID 29443944, 2018). "Regardless of the response pattern, the combination of the responses of SQSTM1, RNASE2, and GATA1 to BYBG supplementation may improve the innate immune capacity to respond to future bacterial infections, which is a hallmark of innate immune training." (PMID 39846553, 2025).
cardiovascular disease (2 papers, 2013 to 2022). "An important result of proteomics approach was the identification of RNase2 and RNase3 only in neutrophils from some of the obese patients with cardiovascular disease." (PMID 35818731, 2022).
immune dysfunction (2 papers, 2021 to 2023). "In this study, we found that RNASE2 was downregulated in IPAH, and it had a positive correlation with neutrophils (r = 0.65) and monocytes(r = 0.75), we suggested that RNASE2 in IPAH was a reflection of immune dysfunction." (PMID 33598484, 2021).
metabolic disorders (1 paper, 2023). "In this study, we found that RNASE2 is a common immune- and metabolism-related biomarker for both MS and IPAH, which suggests that RNASE2 may be responsible for the development of metabolic disorders in both diseases, proving it has an important potential role in diagnosing MS patients with IPAH." (PMID 36635413, 2023).
RNASE2 also shares sentences with these, for which no sentence is quoted: parasitic infections (4 papers); allergic asthma (3); allergic disease (3); airway hyperresponsiveness (2); allergic rhinitis (2); Atopic Dermatitis (2); eczema (2); food allergy (2); Kawasaki disease (2); Obesity (2); ovarian carcinoma (2); Achalasia (1); Allergy (1); Alzheimer disease (1); amyotrophic lateral sclerosis (1); anaphylaxis (1); ANCA-associated vasculitis (1); anemia (1); appendicitis (1); bacteremia (1); brain infarction (1); breast carcinoma (1); bronchiolitis (1); chronic myelogenous leukemia (1); chronic sinusitis (1); colitis (1); eosinophil leukemia (1); eosinophilic esophagitis (1); filariasis (1); fungal infections (1).
A further 30 diseases each share a sentence with RNASE2 in 1 paper.